PRL (prolactin)
Diseases named in the same sentence as PRL in open-access papers (continued):
Sharing a sentence is not in itself a finding about the gene and the disease.
hyperprolactinemia (continued). "Reasons for the association between prolactin and metabolic parameters include direct effects of prolactin on adipose tissue, hyperprolactinaemia-triggered hypogonadism and dopamine-agonist therapy per se." (PMID 33902531, 2021). "A PRL level > 500 ng/ml is virtually diagnostic for a prolactinoma but drug-induced hyperprolactinemia must be excluded." (PMID 34557164, 2021). "Among prolactinoma patients, clinical presentations are associated with either excessive autonomic production of prolactin by the lactotroph cells, leading to hyperprolactinemia, or mass effect caused by tumor size." (PMID 33946142, 2021). "Blonanserin was associated with a lower incidence of hyperprolactinemia, increase in blood prolactin, gamma glutamyl transpeptidase increase, weight increase, increased appetite, and orthostatic hypotension." (PMID 31788985, 2020). "For example, elevated prolactin levels above the normal range (i.e., hyperprolactinemia) such as in the case of prolactinoma have been associated with adverse outcomes including hyperinsulinemia, insulin resistance, and increased body weight." (PMID 32180760, 2020). "Hyperprolactinemia is a well-established cause of hypogonadotropic hypogonadism; PRL acts on kisspeptin-1 neurons expressing the PRL receptor (PRL-R) and is responsible for decreased kisspeptin-1 and GnRH secretion, leading to anovulation." (PMID 32982975, 2020). "Once stress-related hyperprolactinaemia and macroprolactin are excluded, the most frequent cause is a prolactin secreting pituitary adenoma." (PMID 32857272, 2020). "Hyperprolactinemia is a physiologic or pathologic condition that causes hypersecretion of prolactin (PRL) by lactotroph cells." (PMID 32597541, 2020). "In the limited previous reports of ectopic extracranial prolactin secretion in the published literature, ovarian germ cell tumors associated with hyperprolactinaemia had microscopic pituitary elements." (PMID 32857272, 2020). "Accordingly, PRL levels are influenced by the menstrual cycle, menopause, and pregnancy, and any high oestrogen state (e.g., pregnancy) is a potential cause hyperprolactinaemia." (PMID 31847209, 2019). "The median PRL levels were 93.15 ng/mL, 241.8 ng/mL, 74.5 ng/mL, 93.2 ng/mL, and 69 ng/mL for microadenomas, macroadenomas, idiopathic hyperprolactinemia, drug-induced hyperprolactinemia and other causes of hyperprolactinemia, respectively." (PMID 30396878, 2019). "Group C participants who had hyperprolactinemia as the only etiology of RPL were more than the participants of Group B who had increased levels of prolactin associated with latent FGTB." (PMID 32095740, 2019). "A simple medication like bromocriptine or cabergoline, which normalizes serum prolactin levels, has been consistently shown to restore gonadal functions, reverse infertility caused by hyperprolactinemia, and reduces prolactinoma size in majority of patients." (PMID 31208410, 2019). "Increase in bone fracture risk has been specifically linked to the use of hyperprolactinemia-inducing antipsychotics, possibly due to altered bone turnover and changed bone metabolism caused by an elevated prolactin level." (PMID 31019532, 2019). "It is well known that prolactin directly suppresses bone formation, and also causes bone loss associated with hyperprolactinemia during pregnancy and lactation." (PMID 31551490, 2019). "The diagnostic work-up of hyperprolactinaemia includes imaging of the sellar area, which is performed after excluding other common causes of high prolactin (physiological, primary hypothyroidism, drug-induced)." (PMID 31847209, 2019). "Medications and sellar/parasellar masses (prolactin secreting or acting through “stalk effect”) are the most common causes of pathological hyperprolactinaemia." (PMID 31847209, 2019). "Medications and sellar/parasellar masses (prolactin secreting or acting through the “stalk effect”) are the most common causes of pathological hyperprolactinaemia." (PMID 31847209, 2019).
hyperprolactinemia (continued). "In this review, we provide an update on the diagnostic and management approaches for the patient with hyperprolactinaemia and on the current data looking at the impact of high prolactin on metabolism, cardiovascular and immune systems." (PMID 31847209, 2019). "In that situation, this so-called disconnection hyperprolactinemia is thought to result from loss of the inhibitory effect of dopamine on PRL secretion." (PMID 29768629, 2018). "Many antipsychotics cause serum hyperprolactinemia as an adverse side effect; prolactin-Janus kinase 2 (JAK2)-signal transducer and activator of transcription 5 (STAT5) signaling both induces cell differentiation and suppresses apoptosis." (PMID 29778097, 2018). "The association of hyperprolactinemia with the use of antidepressants is known to inhibit the reuse of dopamine, which in turn inhibits prolactin." (PMID 30542321, 2018). "Through the report, we conclude that diagnosis of PCOS should be made only after exclusion of alternative causes like hyperprolactinemia and detailed evaluation should be sought for any significant, unexplained prolactin elevation." (PMID 30250766, 2018). "A retrospective study of 422 psychiatric patients found that antipsychotic therapy was strongly associated with hyperprolactinemia, and that serum PRL levels were affected in a dose-dependent manner." (PMID 29778097, 2018). "Several reports have indicated that chronic alcohol use can cause excessive levels of prolactin in the blood (i.e., hyperprolactinemia) in both men and women." (PMID 28988577, 2017). "Hyperprolactinemia, leading to hearing loss, has been also detected in menopausal women taking hormone replacement therapy containing prolactin." (PMID 29354051, 2017). "In galliformes that express incubation behaviour, hyperprolactinemia is associated with large shift in absolute and relative levels of G-PRL (from about 30% during egg laying to about 70% during incubation behaviour)." (PMID 28107515, 2017). "In alternative, especially when PRL- related symptoms are evident, the associations with dopaminergic medications usually administered for treating hyperprolactinemia (bromocriptine, cabergoline), or with low-dose Aripiprazole, should be considered." (PMID 27209326, 2016). "Pituitary causes include prolactin-secreting pituitary adenoma or disconnection hyperprolactinemia due to a lesion that compresses the pituitary stalk." (PMID 26969187, 2016). "It has been argued that ossification in the interstices of prolactinomas can be caused by the focal intensification of hyperprolactinemia in the systemic circulation or presence of autocrine prolactin within the tumor parenchyma." (PMID 27917338, 2016). "Up to 50 % of women with galactorrhoea have normal prolactin levels, but amenorrhoea associated with galactorrhoea strongly suggests hyperprolactinaemia." (PMID 27716353, 2016). "Diagnosis of hyperprolactinaemia and identification of its cause can be based on medical history, physical examination, clinical features, serum prolactin levels, biological investigations, and imaging of the pituitary region." (PMID 27716353, 2016). "As both endometriosis and hyperprolactinemia are associated with infertility it became an attractive theory to implicate raised PRL levels as the cause for infertility in women with endometriosis." (PMID 26000006, 2015). "Hyperprolactinemia is known tobe one of the causes of pseudopregnancy, namelycontinuous diestrus, by stimulating and maintainingCL in rodents since prolactin has a luteotropicactivity." (PMID 26644861, 2015). "Nine patients showed hyperprolactinemia preoperatively due to either the underlying prolactinomas (five with prolactin level > 100 mg/L) or stalk effect from the mass lesion." (PMID 26623212, 2015). "Hyperprolactinaemia is mainly associated with antipsychotics, such as risperidone, which predominantly block the dopamine D2 receptor, the receptor that modulates prolactin release from the pituitary." (PMID 26491441, 2015).
hyperprolactinemia (continued). "Cases of pituitary adenoma associated with increased production of both ACTH and PRL, causing apparent Cushing's disease and hyperprolactinemia, are extremely rare." (PMID 25506361, 2014). "Although antipsychotic drugs are a common cause of hyperprolactinaemia, other studies in drug-naïve patients have also shown increased prolactin levels in PD and HR subjects." (PMID 24586772, 2014). "Transient elevation of serum prolactin during the symptomatic period and its rapid normalization with resolution of symptoms favours the diagnosis of a transient hyperprolactinaemia as the cause for her galactorrhoea." (PMID 25518745, 2014). "As antipsychotic treatment generally causes hyperprolactinemia, measuring prolactin levels in drug-naïve patients is a useful method of assessing their relationship with schizophrenia itself." (PMID 24800074, 2014). "Galactorrhea can be also caused by anti-psychotics that cause hyperprolactinemia by blocking dopamine receptors responsible for control of prolactin release." (PMID 23456048, 2013). "In contrast to our findings, studies including pathological hyperprolactinemia caused by PRL-secreting tumors (prolactinomas) showed that, after treatment with dopamine agonists, reduced PRL concentrations led to increased insulin sensitivity." (PMID 23517652, 2013). "The mechanism of hyperprolactinemia is that antipsychotics block the dopamine D2 receptor of lactotrophs in the anterior pituitary and the prolactin secretion inhibiting function and consequently causes hyperprolactinemia." (PMID 23690768, 2013). "Both cyclosporine-A and feldipine (a calcium antagonist) are reported to induce hypertrophy by causing hyperprolactinemia supported by a raised serum prolactin level post mammoplasty." (PMID 20701786, 2010). "Six years later, the anaemia was resolved when the prolactin levels were reduced, making it reasonable to deduce that hyperprolactinaemia was the cause of the anaemia all along." (PMID 20205855, 2010). "The subsequent literature review documented an interesting association between prolactin and rheumatic diseases and in particular, hyperprolactinemia and SLE." (PMID 19852783, 2009). "If prolactin levels are elevated in the presence of potentially prolactin-related adverse events (PPAEs) the cause of hyperprolactinemia should be determined, and consideration should be given to changing to a prolactin-sparing antipsychotic." (PMID 19210771, 2009). "Treatment options for hyperprolactinemia include correction of underlying causes or suppression of PRL secretion in the case of a secreting tumor." (PMID 23675050, 2007). "Elevated levels of circulating prolactin (hyperprolactinemia) have long been associated with pituitary tumors, but more recently prolactin has been reported in association with a variety of additional cancers, including breast, prostate, and colon carcinoma." (PMID 18060075, 2007). "There was also no increase in PTHrP during r-hPRL treatment, an observation that is surprising in light of the association between PTHrP and prolactin in lactating women and women with hyperprolactinemia and interventional studies in animals." (PMID 17650319, 2007). "Moreover, infundibular lesions commonly cause mild hyperprolactinemia through the stalk effect; therefore, the patient’s normal prolactin level is a key finding." (PMID 41497147, 2026). "Observational studies have reported that weight-loss interventions are associated with reduced circulating prolactin levels, whereas dopamine agonists, which suppress prolactin secretion, improve metabolic and endocrine abnormalities in patients with established hyperprolactinemia." (PMID 41918976, 2026). "In BALB/c mice that carry a transgene for the heavy chain of a pathogenic anti‐DNA antibody, inducing moderate hyperprolactinemia (resulting in a twofold increase in serum PRL levels) enhances the population of autoreactive B cells exhibiting a follicular phenotype." (PMID 41476991, 2025).
hyperprolactinemia (continued). "In addition, patients have transient PRL elevation, and the most common endocrine disorder caused by ES is hyperprolactinemia." (PMID 40909229, 2025). "By lowering PRL concentrations, bromocriptine may help suppress the autoimmune processes linked to hyperprolactinemia." (PMID 41476991, 2025). "However, hyperprolactinaemia in a group at risk of mental illness and later developing psychosis raises the question of the aetiopathogenic role of prolactin in the onset of psychosis." (PMID 40896214, 2025). "The clinical manifestations of hyperprolactinemia and hypogonadism may pose diagnostic challenges; therefore, in addition to monitoring prolactin level changes, recognizing associated ADE symptoms is crucial." (PMID 39833706, 2025). "Our observations on the effect of PRL on cardiovascular function have shed new light on the association of hyperprolactinemia with an impaired hemodynamic profile, which may result in the early development of cardiovascular complications." (PMID 41244055, 2025). "Although no histopathological confirmation was obtained, the diagnosis of giant prolactinoma was made based on the presence of markedly elevated prolactin (PRL) levels, characteristic MRI findings, and the exclusion of other potential causes of hyperprolactinemia." (PMID 40599499, 2025). "In turn, the impact of cabergoline on glucose homeostasis, plasma lipids and non-lipid risk factors was more pronounced in young women with mild or moderate hyperprolactinemia and normal vitamin D homeostasis than in age- and prolactin concentration-matched women with vitamin D deficiency." (PMID 40507082, 2025). "In contrast, men can also develop hyperprolactinemia, but the clinical sequelae differ – high prolactin in men may cause sexual dysfunction (e.g., decreased libido, erectile problems) and sometimes gynecomastia, though gynecomastia can occur in women as well." (PMID 40589655, 2025). "Hyperprolactinemia and hyperinsulinemia, whether pre-existing or generated by elevated prolactin levels, may be regarded as risk factors for the development of carbohydrate metabolism problems." (PMID 40362476, 2025). "Additionally, surgical treatment often results in a more rapid normalization of hyperprolactinemia compared to DA therapy alone, providing faster symptomatic relief and reducing the risk of long-term complications associated with elevated prolactin levels." (PMID 39202626, 2024). "In most cases, hyperprolactinemia is caused by pregnancy, hypothalamic-pituitary disconnection, or prolactin-secreting pituitary adenomas (prolactinomas), but may also be secondary to the use of certain medications." (PMID 38578472, 2024). "Interestingly, iron deficiency is associated with increased serum prolactin and/or even hyperprolactinemia." (PMID 39201626, 2024). "Due to the fact that macroprolactin interferes with many immunological assays that are commonly used for the detection of PRL, macroprolactinemia is a frequent cause of misdiagnosed hyperprolactinemia in clinical practice for the treatment of ovulation disorders." (PMID 38396659, 2024). "Given that a significant portion of patients experienced adverse effects in this category, many of which are symptoms associated with hyperprolactinemia, we hypothesized that elevated prolactin levels may induce these effects." (PMID 38998877, 2024). "Hyperprolactinemia unrelated to lactation is a common cause of amenorrhea in women of a childbearing age, and a consequent decrease in the gonadotropin-releasing hormone (GnRH) by a high prolactin level can result in decreased bone mineral density." (PMID 38338751, 2024). "Notably, prolactin values above 60-80 ng/mL suggest another underlying cause of hyperprolactinemia that should be actively investigated." (PMID 38578472, 2024). "In patients without a gestational history, IGM might be associated with high levels of prolactin, suggesting a potential role of hyperprolactinemia in its pathogenesis." (PMID 39410007, 2024).
hyperprolactinemia (continued). "Hyperprolactinaemia (serum prolactin > 25ng/ml) is a known cause of anovulation and infertility." (PMID 39092016, 2024). "In addition, hyperprolactinemia, or high levels of prolactin in the blood, has also been linked to an increased risk of pregnancy loss, particularly those who have a history of recurrent miscarriages." (PMID 39763651, 2024). "The excessive secretion of prolactin, a condition called hyperprolactinemia, may cause galactorrhea, infertility, and menstrual disruption in women." (PMID 39599674, 2024). "Moreover, the pathological causes of hyperprolactinemia include prolactin-producing pituitary adenomas, hypothalamic/pituitary tumors, hypothalamic infiltrative diseases, and hypothyroidism." (PMID 38338751, 2024). "Hyperprolactinemia was likely to be caused by the co-secretion of GH and prolactin from the tumor." (PMID 37886642, 2023). "In addition, hyperprolactinemia in pituitary tumor in which patients often have headaches supports the idea that increased levels of prolactin has been linked to increased migraine attacks." (PMID 37190874, 2023). "In women, most studies found that hyperprolactinemia is associated with a multidimensional alteration of sexual function, which could be reverted by normalizing PRL levels." (PMID 37204690, 2023). "Furthermore, the ratio of prolactin levels to tumor volume (PVR) was likewise shown to be predictive for the differentiation of prolactinomas from other types of sellar lesions causing hyperprolactinemia." (PMID 36147567, 2022). "Higher PRL levels are associated with higher insulin sensitivity and a lower incidence of type 2 diabetes mellitus, which led to a re-evaluation of current thresholds for normal PRL levels and hyperprolactinemia." (PMID 36157442, 2022). "A study using female mice receiving continuous infusions of prolactin to induce hyperprolactinemia showed prolonged elevated prolactin caused abrogation of the oestrous cycle and a decrease in FSH, luteinizing hormone (LH) and ovum lutea, resulting in anovulation." (PMID 36619589, 2022). "Risperidone and aripiprazole exhibited the strongest associations with hyperprolactinemia and decreased blood PRL according to the disproportionality analyses, and both were identified as co-administered drugs that influenced PRL levels during OLZ treatment by SHAP analyses." (PMID 36313772, 2022). "Before anti-psychotic therapy, recording a baseline prolactin level may help in determining whether a patient’s elevated level is due to medication-induced hyperprolactinemia or other causes." (PMID 35223307, 2022). "However, data associating hyperprolactinemia with other comorbidities such as obesity, metabolic syndrome, diabetes, and cardiovascular risk raise the question if serum PRL levels should be always normalized." (PMID 36704037, 2022). "The positive correlation between PDW and the log-transformed PRL in our study suggests that hyperprolactinemia in OLZ-treated patients might be associated with the increased risk of thromboembolic events because PDW increases during platelet activation." (PMID 36313772, 2022). "The discovery of the dopamine inhibitory effect on PRL secretion and lactotroph tumour growth more recently led to an increasing use of DAs in the endocrinological field for the management of disorders associated with hyperprolactinemia." (PMID 35460460, 2022). "A previous animal study performed on 50 adult female rats found that hyperprolactinemia induced estrogen deficiency with a direct effect on the bone and caused bone loss in women, and estrogen and prolactin could increase serum 1,25(OH)2D3 and PTH levels." (PMID 36313749, 2022). "Secondary hyperprolactinemia due to stalk effect may cause mild or moderate elevation of serum prolactin levels, but severe elevation is unlikely." (PMID 35928122, 2022).